CD4 (CD4 molecule)
Diseases named in the same sentence as CD4 in open-access papers (continued):
Sharing a sentence is not in itself a finding about the gene and the disease.
tumor (continued). "Herein, PD-L1 showed heterogeneous expression in different tumor regions in this case, and the variation in its expression intensity was consistent with the infiltration levels of CD4+ T cells, CD8+ T cells, and Tregs." (PMID 38957460, 2024). "Here we used our mAITL preclinical model to validate the generation of anti-CD4 CAR T cells in vivo exclusively expressed by the CD8 T cells in the AITL tumor environment." (PMID 39272178, 2024). "In untreated mice, the Treg percentage among CD4 T cells was 18.6% in blood, 23.8% in spleen, 20.6% in dLN, and 49.5% in tumor tissues." (PMID 38932362, 2024). "CD4+ T cells mainly mediate anti-tumour immunity by facilitating CD8+ CTL and antibody responses, by expressing key molecules that are associated with cytolytic granules such as granzymes or perforin or via direct cytotoxicity to tumour cells." (PMID 38475858, 2024). "Consistently with the reduced binding of IL-2v to CD25, CEA-IL-2v induced a CD8+:CD4+ ratio toward CD8+ T cells both in the periphery and in the tumor associated with single-agent and combination efficacy in syngeneic models." (PMID 39204319, 2024). "Following the injection of carboplatin, MDSCs stimulated IL-13/IL-33 via the VCAM/RANTES pathway, facilitating CD4+ T cells to convert into Tregs and encouraging Tregs aggregation at tumor locations." (PMID 39372416, 2024). "Although it is clear that CD4+ T cells provide critical assistance for the anti-tumour immune response, the antigen repertoire that is recognized by CD4+ T cells in the TME remains relatively unexplored." (PMID 38475858, 2024). "Consistent with the trend of the proportion of CD4+ T cells in tumor tissues, the proportion of CD4+ T cells in spleen tissues was the highest in the double-drug micelle PPH@CR group, which was significantly better than that in other groups." (PMID 39014462, 2024). "Under the ambiance of HPV+ tumor cells, CD4+T cells manifested an upregulated expression of CXCL13 and IFNγ, indicating the enhanced differentiation toward CXCL13+ CD4+ T cells and TH1 phenotype." (PMID 39105803, 2024). "In fact, the effectiveness of cancer immunotherapy hinges on the interactions between DCs and CD8+ and CD4+ T cells, as well as other immune cells in the tumor microenvironment (TME)." (PMID 38523774, 2024). "Tumor-infiltrating lymphocytes (TILs), such as CD8+ and CD4+ T cells, have been associated with better response to immunotherapy." (PMID 38673829, 2024). "Tregs, a subgroup of CD4+ T cells, are powerful immunosuppressive cells that inhibit anti-tumour immunity by inhibiting effector T cell (Teffs) activity." (PMID 38475858, 2024). "In BRCA1/2mut ovarian cancer, a proliferating tumor-cell subpopulation has been reported to be associated with enhanced spatial tumor-immune interactions by CD8 + and CD4 + T cells." (PMID 38918817, 2024). "DCs capture tumor antigens, process them, and present antigenic peptides to CD4+ and CD8+ T cells while NK cells play a role in immunosurveillance by directly killing tumor cells and producing cytokines." (PMID 38349050, 2024). "Obviously, cGAS EV injection elevated the levels of CD3+CD8+ (cytotoxic) and CD3+CD4+ (helper) T cells in tumor tissues." (PMID 38518087, 2024). "We observed a significant increase in effector CD4+ T cells in the tumor-draining lymph nodes, particularly in the group treated with both Tpst2 knock-down and anti-PD1." (PMID 39095793, 2024). "Using Tumor Immune Estimation Resource 2.0, the infiltration levels of B cells, CD4 + T cells, CD8 + T cells, neutrophils, macrophages, and myeloid dendritic cells were retrieved from patients with pancreatic head and body/tail cancers." (PMID 39187784, 2024). "Correlation based on infiltration density of the different immune cells, reflecting their associations within or between tumor and stroma, we observed three clusters - stromal and tumor B cells, Treg cells and macrophages, and CD4 T cells and CD8 T cells." (PMID 39184073, 2024).
tumor (continued). "Combined therapy promoted M1 macrophage polarization, significantly increasing the density of infiltrating CD8+/CD4+ T cells in the tumor center." (PMID 38175694, 2024). "PD-1, also known as CD279 or PDCD1, is a transmembrane protein encoded by the PDCD1 gene and expressed in tumor-specific T cells (CD8+ cytotoxic T cells and CD4+ Th1 cells), NK cells, B cells, monocytes, and dendritic cells." (PMID 38893211, 2024). "Our findings suggest there was a strong association between cDC1RS and CD4 and CD8+ T cell-mediated immune responses, potentially leading to more effective T-cell priming in the tumor microenvironment." (PMID 39015755, 2024). "It has been revealed that IL-6 trans-signaling via sIL-6R derived by myeloid cells attenuates CD4+ T helper type 1 (Th1) cell differentiation in tumor-bearing mice, leading to defective anti-tumor responses." (PMID 38182653, 2024). "In fact, a melanoma mRNA neoantigen vaccine originally designed to contain only CD8+ T cell epitopes relied on unexpected vaccine-induced CD4+ T cell responses for tumor eradication." (PMID 39040850, 2024). "We then examined how depletion of CD4+ T cells impacts the tumor-controlling potential of CD8+ TILs." (PMID 39185202, 2024). "The main factor that HM‐NPs significantly delay the tumor growth is the increased infiltration of CD4+ and CD8+ T lymphocytes into the tumors, and eventually the tumors in HM‐NPs group showed extensive apoptosis and necrosis compared to the other groups." (PMID 38353384, 2024). "Immune analysis indicated a negative correlation between high-risk score and the abundance of most tumor-infiltrating immune cells, including dendritic cells, CD8+ T cells, CD4+ T cells, and B cells." (PMID 38602575, 2024). "SCFAs, particularly butyrate, have immunomodulatory properties that can influence anti-tumor responses by regulating the levels of immune-suppressing Tregs and tumor-killing CD4 + and CD8 + T cells." (PMID 39030525, 2024). "We also detected a lower relative abundance of MDSC populations and CD4+ Tregs within CR705Parp7KO tumours, further suggesting a shift towards a less immunosuppressive TIL repertoire." (PMID 39867896, 2024). "Treatment with cps is also accompanied by accumulating some splenocytes, including macrophages, B cells, NK cells, and CD4+ T cells, and decreasing the number of Foxp3+ CD4+ T regulatory cells in the tumor microenvironment." (PMID 38109851, 2024). "As expected, we observed complete depletion of total CD4+ T cells and Tregs (defined as Foxp3+ CD25+ CD4+ T cells) in the tumor and TdLN in both the Tx + ɑCD4 and the ɑCD4 groups." (PMID 38429261, 2024). "The presence of plasma cells was associated with the highest levels of CD8+, CD4+, and CD20+ tumor-infiltrating lymphocytes (TILs), as well as the upregulation of numerous cytotoxicity-related gene products." (PMID 38502270, 2024). "In a study with 39 patients with BCC, Pellegrini and colleagues showed that the number of IL-17-producing CD4+ T lymphocytes correlated positively with the severity of the inflammatory infiltrate in the tumor." (PMID 38690280, 2024). "In ACT, CD8 T cells infiltrating the tumor microenvironment are considered directly cytotoxic while CD4 T cells have an ancillary role." (PMID 39629126, 2024). "Consistent with previously reported results, patients with enriched CD4+ and CD8 + T cells interacting with tumor cells were associated with better outcome and the myeloid component/M2 macrophage were critical for T cells." (PMID 38898200, 2024). "In this way, we were able to turn the “cold tumor” into the “hot tumor”, with higher CD4+ T and CD8+ T cells infiltration, higher immune stimulating factors secretion, and an effective systematic immune activation." (PMID 38757665, 2024). "ACT of Treg cell-depleted CD4+/CD8+ T cells from LDVax-treated WT mice into T3 tumour-bearing, immunodeficient Rag2−/− mice was sufficient to induce T3 rejection." (PMID 39048822, 2024).
tumor (continued). "Depletion of both CD8+ and CD4+ T cells completely abolished the anti-primary and -rechallenged tumor responses elicited by the in situ cancer vaccine, while depletion of either cell type caused only a modest reduction." (PMID 38678042, 2024). "The expression of TGF-β induces the differentiation of tumor-infiltrating CD4+ naïve T cells into Tregs, thereby suppressing effector T cell function and inhibiting the anti-tumor immune response." (PMID 38426090, 2024). "We observed increased cell–cell interactions of CD8 Tcm cells and decreased interactions of CD4 Tem/eff cells with macrophages, tumor cells, and DCs in the TOFU-ACT treated mice compared to untreated." (PMID 38268001, 2024). "B cells, with the CD19 as surface marker, mainly secrete antibodies against tumor-associated antigens and coactivate CD8+ T cells in conjunction with CD4+ T cells." (PMID 38482008, 2024). "This is particularly important because the CD4 + T cell helper cells have been shown to be crucial for sustained anti-tumor immunity." (PMID 39160595, 2024). "The CD8+ cell types cause tumor cell destruction and are dominant in the BC microenvironment, whereas CD4+ subpopulations can produce either pro- or anti-tumor activity." (PMID 39050852, 2024). "At this timepoint, there was a paucity of both immune cells and tumor cells, including a decrease in CD4+ T cells and Tregs, with mostly stromal and endothelial cells present, likely representing a wound healing environment and the effects of CRT." (PMID 38181044, 2024). "In this respect, Th2, a specific subset of CD4+ T cells, have long been known to promote tumor growth and metastasis by suppressing the immune system." (PMID 39544930, 2024). "In more details, the high amount of pancreatic tumor antigens released by CD8+ effector T cells during primary cps therapy can elicit the secretion of tumor‐specific IgG, along with long lasting CD4+ T cell memory." (PMID 38109851, 2024). "We investigated the CD4+ T cell subsets in RocA-treated tissues from tumor-bearing mice via intracellular stain flow cytometry." (PMID 38833034, 2024). "CD4+ T-helper (Th) cells are central to adaptive immunity, orchestrating both pathogen and tumor responses through cytokine production." (PMID 39769334, 2024). "The exhaustion marker PD-1 was only inhibited in tumor-infiltrating CD4+ and CD8+ T harvested from anti-PD-1-treated tumors." (PMID 38643157, 2024). "In line, the analysis of the sequencing data using the CellChat Cell-Cell Communication Atlas Explorer, unraveled that MCs communicate predominantly with fibroblasts, tumor cells, Cd4+ T cells, and macrophages." (PMID 38942797, 2024). "CRC patients with POLE mutation were reported to have positive treatment responses with immune checkpoint inhibitors, partly because of the high CD4+ T cell infiltrations and increased expressions of pro-inflammatory cytokines in the tumor microenvironment." (PMID 39007151, 2024). "Subsequently, the analysis of TILs (tumor infiltrating lymphocytes) showed that cluster-A had abundant immune cell infiltration, including B, CD4 T, dendritic, gamma delta T, and natural killer cells." (PMID 38669381, 2024). "The key players in the activation of antigen-specific immune responses are antigen-presenting cells, dendritic cells in particular, which mediate antitumor immunity through the activation of CD8+ and CD4+ T-cells in the tumor microenvironment." (PMID 38540312, 2024). "The frequency of CD4+ lymphocytes and their follicular subsets also showed significant variations in draining lymph nodes of patients with different tumor shapes." (PMID 39223192, 2024). "Patients with more advanced clinical stages showed shorter distances between CD4+Tregs and tumor cells in IM and TC, and CD4+T cells in IM, while the distance between CD4+Tregs and CD8+T cells in IM and TC was prolonged." (PMID 39093404, 2024).
tumor (continued). "Bossio and colleagues examined tumor-infiltrating CD39+CD4+ T cells obtained from patients with BC, finding that these cells exhibit features of exhaustion while retaining the capacity to produce effector cytokines." (PMID 39735530, 2024). "Similarly, the increase in activated CD4+ memory T cells in high‐risk samples could reflect a compensatory immune response to tumour progression, or alternatively, these cells might be indicative of a tumour‐promoting inflammatory environment." (PMID 38973477, 2024). "Analysis of intratumoral TILs (iTILs) within the cancer cell nests using HALO software showed that administration of the anti-CTLA-4 Ab significantly increased the infiltration of CD4+ T cells into the tumor." (PMID 39106430, 2024). "Of note, Ki67 expression was similar between tumor-infiltrating and circulating CD4+ T cells but was increased in CD8+ T cells in metastases compared to the circulation (p<0.05)." (PMID 38384469, 2024). "CD4+/CD25+/FOXP3+ Treg cells suppress the immune system and promote tumor progression by reducing the anticancer immunity of CD4+ T or CD8+ effector T cells." (PMID 39534095, 2024). "Several cells were included in this validation, namely B cells, CD8+ T cells, CD4+ T cells, macrophages, neutrophils, and dendritic cells, and tumor purity was also included in patients with GBM." (PMID 39139341, 2024). "Tumor‐infiltrating cells (including NK, CD4+, and CD8+ cells), which negatively associated with the growth of tumor, were associated with increased CXCL10 levels." (PMID 39443817, 2024). "Depletion of either CD4+ or CD8+ T cells abrogated the tumor suppression induced by intrapleural injection of LLC-EVs." (PMID 38250037, 2024). "Consistent with the results obtained from our TMAs, patients harboring NLRC4-null tumors (through genetic arm-level deletion) exhibited decreased CD4+ T cell tumor infiltration versus diploid normal tumors (P < 0.01)." (PMID 38652550, 2024). "Increased numbers of CD4(+) Tregs expressing the transcription factor FoxP3 in malignant tumors promote tumor progression by suppressing effective anti-tumor immunity." (PMID 39409959, 2024). "nTregs are mainly CD4+ Tregs that mature after IL-2 and IL-15 stimulation in the thymus and maintain immune tolerance in peripheral areas of inflammation or tumor tissues, and account for approximately 1–3% of total CD4+ T lymphocytes." (PMID 39329710, 2024). "CD4 + T cell infiltration in tumor tissues was negatively correlated with metabolic volumetric parameters." (PMID 38627864, 2024). "Using a non-T cell receptor transgenic, immunocompetent tumor model, researchers demonstrated that the eradication of aggressive cancers through T cell targeting of tumor stroma crucially depends on the cooperation between CD4+ and CD8+ T cells." (PMID 39338178, 2024). "We found that naïve and tumor-rejecting mice contained comparable frequencies of CD4+ and CD8+ T cells with a similar distribution of naïve and memory subsets." (PMID 38243308, 2024). "IT CXCL9/10-DC led to an increased depth of tumor penetration by CD4+ T cells when compared to CD8+ T cells." (PMID 38518770, 2024). "CD4+ Th1-dominant immune response rapidly elicited by cryo-thermal therapy was observed in tumor patients with metastasis post treatment in former researches." (PMID 38827732, 2024). "Altogether, these data showed that BCCs and SCCs share a dense T cell infiltrate of similar composition regarding broad T cell subsets, namely, CD8+, CD4+, and FoxP3+, essentially confined to the tumor periphery." (PMID 38891095, 2024). "In parallel, mIF showed an aggregation of CD4+/FOXP3+ Treg cells in tumor tissues of subtype A, but almost invisible in the tumor tissue of the other three subtypes." (PMID 39060379, 2024). "In the MFC tumor model, CD4+ T cells dominated the immune landscape, while B cells were most prevalent in the Hepa1-6 model." (PMID 38554776, 2024).
tumor (continued). "Paired PBMC-tumor analysis showed moderate correlations between peripheral CD4+ T and NK cells with their counterparts in tumors." (PMID 38653982, 2024). "Tumor samples were clustered and annotated into eight distinct clusters, identified as B cells, conventional CD4+ T cells, CD8+ T cells, exhausted CD8+ T cells, dendritic cells (DCs), monocytes or macrophages, myofibroblasts, and NK cells." (PMID 38279987, 2024). "Effector T cells and CD4+ T cells were highly enriched in tumor nests and stroma in both the CT and IM in the PRSlow group." (PMID 38773976, 2024). "This, in turn, induced the emigration of enterotropic α4β7+CD4+ regulatory T 17 cells into the tumor." (PMID 38361936, 2024). "This suggests that RPT to tumor cells induces signaling to CD4+ T cells that increases viability, but also increases immune inhibitory signals, potentially indicating a need for immunotherapy to block the upregulated immune checkpoint pathways." (PMID 39355211, 2024). "In the tumor microenvironment, CD4+ and CD8+ T cell number, including their subpopulations (cytotoxic CD8+ T cells and Th1 cells) had a time-dependent increase in the group with acute T. gondii infection compared with the group without infection." (PMID 38835064, 2024). "Results showed that TFP tumors had a lower abundance of immune cell infiltration, especially cells specialized for anti-tumor reactivity (e.g., activated CD4 T cell, activated CD8 T cell, and central memory CD8 T cell)." (PMID 38331878, 2024). "Although considerable attention has been given to CD8+ T-cells, the importance of CD4+ T-cells in tumor management and responses to immunotherapeutic approaches is also becoming increasingly evident." (PMID 39682280, 2024). "Correlation analysis between the feature genes and immune cell signatures revealed that MAP2K1 and PRKACB are positively correlated with CD4+ T cells and immune score, both of which are crucial for anti-tumor immunity." (PMID 39835132, 2024). "Tumor infiltration is associated with six cells B cells, CD8+, CD4+, macrophages, neutrophils, and dendritic cells." (PMID 38504096, 2024). "In contrast, CD4+ FoxP3+ regulatory T cells impede anti-tumor immunity by inhibiting cytotoxic T lymphocyte activation." (PMID 38560504, 2024). "First, deletion of MHC-II molecules on cDC1s impaired tumor rejection, consistent with the need for interaction of CD4 T cells and cDC1s to effectively prime CD8 T cells." (PMID 38903502, 2024). "The low‐PIS group appeared more capable of recruiting CD4 or CD8 T cells into the TME to kill tumour cells." (PMID 38946232, 2024). "OX40 participates in CD4+ T cell processes and opens new avenues for tumor immune-targeted therapies, despite the need for further refinement and discovery in OX-40 studies." (PMID 39329710, 2024). "In tumor-infiltrating immune analysis, we have discovered FAT4 mutation to involve more infiltration of CD4 memory-activated T cells, follicular helper T cells, and gamma delta T cells, while less infiltration of naïve B cells and Tregs." (PMID 39323626, 2024). "Taken together, these results underscored the importance of immune features within the tumor ecosystem and provided prognostic significance of CD4+ T cells for HNSCC patients." (PMID 39093451, 2024). "CD161 was mainly expressed by tumor‐infiltrating CD4+ and CD8+ T cells, with negligible expression by TCs." (PMID 38502058, 2024). "Five kinds of tumor-infiltrating immune cells, B cells, CD4 T cells, CD8 T cells, macrophages, and neutrophils, were analyzed." (PMID 38485995, 2024). "CD39, encoded by ENTPD1, is present on various cell types, including tumor cells, tumor-specific CD4 and CD8 T cells, endothelial cells, fibroblasts, and cells of myeloid lineage." (PMID 38785789, 2024).